CNTLN (centlein)
Description:
Required for centrosome cohesion and recruitment of CEP68 to centrosomes.
Synonyms: C9orf101; C9orf39; FLJ20276; bA340N12.1; OTTHUMG00000019597
Tractability: PROTAC: ubiquitination databases record sites on it.
Gene: Protein-coding gene on chromosome 9 (17,134,982 to 17,503,923, forward strand). Ensembl gene ENSG00000044459.
Subcellular location: Cytoplasm, cytoskeleton, microtubule organizing center, centrosome, centriole
Subcellular location (Human Protein Atlas): Centrosome; Cytosol; Nucleoplasm
Gene Ontology:
Molecular function: protein domain specific binding; protein kinase binding; protein-macromolecule adaptor activity
Biological process: centriole-centriole cohesion
Cellular component: centriole; centrosome; cytoplasm; extracellular exosome; sperm head-tail coupling apparatus
Genetic constraint (gnomAD): Loss-of-function variants: 128 observed, 103.56 expected, observed/expected ratio (o/e) 1.24, 90% interval 1.07 to 1.43. The synonymous counts are far from expectation, so gnomAD's model fits this gene poorly and the ratio says little. Missense variants: 1,488 observed, 1,139.4 expected, observed/expected ratio (o/e) 1.31, 90% interval 1.25 to 1.36. Synonymous variants: 525 observed, 409.16 expected, observed/expected ratio (o/e) 1.28, 90% interval 1.19 to 1.38.
Homologues: Orthologues: chimpanzee CNTLN (99% identical), macaque CNTLN (95% identical), dog CNTLN (87% identical), pig CNTLN (85% identical), rabbit CNTLN (81% identical), mouse Cntln (77% identical), rat Cntln (72% identical), tropical clawed frog cntln (46% identical), zebrafish cntln (29% identical).
Diseases named in the same sentence as CNTLN in open-access papers:
CNTLN is named in the same sentence as 31 diseases in open-access papers, as found by Europe PMC text mining. Sharing a sentence is not in itself a finding about the gene and the disease. The quoted sentences say what the papers report.
breast carcinoma (4 papers, 2015 to 2025). "TG (thyroglobulin) hypermethylation has been associated with aggressive tumor behavior in breast cancer, and CNTLN, hypermethylated within gene bodies in our study, has been detected in epithelial OC cell lines, although its functional role remains unclear." (PMID 40563675, 2025). "This analysis indicates that the predicted PTB-related genes including ICAM1, CRHBP, PLAGL1, EGR2, CNTLN, and DKK1 play an important role in preforming biological activities associated with PTB, infant disease, and possibly breast cancer, due to the gestational age-induced." (PMID 36788602, 2023). "By joint analysis of gene expression data from previous studies, we constructed interrelationships of mainly CRHBP, ICAM1, PLAGL1, DNMT1, CNTLN, DKK1, and EGR2 with preterm birth, infant disease, and breast cancer." (PMID 36788602, 2023). "Importantly, CNTLN was reported as a PTB-related gene, and PIN1 involves inhibition of breast cancer." (PMID 36788602, 2023).
Obesity (3 papers, 2023 to 2025). Accumulation of substantial excess body fat. "The SH3GL2 gene is involved in synaptic vesicle endocytosis and lipid binding and modification and, together with CNTLN, has been associated with an obesity index in pigs." (PMID 40646437, 2025).
acephalic spermatozoa syndrome (1 paper, 2021). "Here the authors demonstrate that CENTLEIN links and controls the interaction between SUN5 and PMFBP1, indicating that its impairments might be associated with acephalic spermatozoa syndrome." (PMID 34389728, 2021). "We demonstrate that CENTLEIN directly interacts with both SUN5 and PMFBP1, two proteins localized in the HTCA and related with acephalic spermatozoa syndrome." (PMID 34389728, 2021).
cognitive decline (1 paper, 2022). "Hohman’s group revealed that the gene levels of CNTLN in the heart are associated with cognitive decline dependent on amyloid." (PMID 36466608, 2022).
depression (1 paper, 2024). "In addition, rs263575 [BNC2/CNTLN] had a marginally significant indirect effect on broad depression among females but not males, and rs2402273 [LSM8/CTTNBP2] had a marginally significant indirect effect on broad depression among males but not females." (PMID 38790194, 2024).
male infertility (1 paper, 2021). The inability of the male to effect fertilization of an ovum after a specified period of unprotected intercourse. "To further explore the cause of the male infertility, we first examined the Centlein−/− testis at gross and histological levels." (PMID 34389728, 2021). "Therefore, disruption of Centlein leads to the production of acephalic spermatozoa in mice, which may be responsible for the Centlein−/− male infertility." (PMID 34389728, 2021).
Sepsis (1 paper, 2023). Sepsis is defined as life-threatening organ dysfunction caused by a dysregulated host response to infection. "Under sepsis condition, differentially overexpressed CNTLN, ICAM1, and PLAGL1 in PTB were consistently observed." (PMID 36788602, 2023).
CNTLN also shares sentences with these, for which no sentence is quoted: tumor (5 papers); cancer (4); Joubert syndrome (2); Leber congenital amaurosis (2); microcephaly (2); Alström syndrome (1); Azoospermia (1); B-cell lymphomas (1); cardiomyopathy (1); ciliopathies (1); dwarfism (1); meningioma (1); metabolic syndrome (1); MOPD type II (1); myelodysplastic syndrome (1); nephronophthisis (1); neuroblastoma (1); Primary microcephaly (1); Retinal dystrophy (1); rheumatic disease (1); sarcoidosis (1); Seckel syndrome (1); Sjögren's syndrome (1); systemic lupus erythematosus (1).